CD28 (CD28 molecule)
Diseases named in the same sentence as CD28 in open-access papers (continued):
Sharing a sentence is not in itself a finding about the gene and the disease.
tumor (continued). "But T cells transduced anti-CD20scFvFc/CD28/CD3ζ gene had superior ability to lyse the CD20-positive tumor cells compared to T cells transduced anti-CD20scFvFc gene." (PMID 20815894, 2010). "The ATV-NDV can then be combined easily with bispecific antibodies (bsAbs) binding to the HN protein for introducing anti-CD3 and anti-CD28 antibodies at the surface of the tumor vaccine to obtain the NDV-based tumor vaccine of the second generation." (PMID 21403859, 2010). "In this study, we observed that stimulation of tumor-specific CTLs through the TCR/CD3 complex and co-stimulation molecule CD28 resulted in suboptimal proliferation and subsequent loss of proliferative potential." (PMID 21124930, 2010). "In colorectal cancer, tumor-infiltrating lymphocytes (TIL) lack CD28 in contrast to those in normal colon interstitium." (PMID 15613231, 2004). "Engineered T-cells co-delivering CD28 activation in addition to the T-cell receptor (TCR) subunit CD3-ζ are more effective to activate an anti-tumor response in vivo than T-cells with TCR-CD3-ζ only." (PMID 15613231, 2004). "Emerging evidence suggests that incorporating a third specificity, particularly targeting co-stimulatory molecules such as CD28, 4-1BB, or OX40, in addition to CD3 on T cells and a tumor-associated antigen (TAA) on cancer cells, can enhance T-cell activation and prevent exhaustion." (PMID 41488284, 2026). "Notably, NKG2D/CD28& MSLN CAR-T cell group showed enhanced tumor suppression, with a significant difference observed when compared to the traditional MSLN CAR-T cell group." (PMID 40181405, 2025). "Moreover, CD28 signalling domains are also widely incorporated into the design of CAR T cells to enhance CAR T cell function in tumour immunotherapy." (PMID 40496752, 2025). "Furthermore, CD28 signalling enhances IS formation by strengthening the adhesion between T-cells and APCs (including tumour cells)." (PMID 40361472, 2025). "This may be attributed to an increased proportion of dysfunctional or non-tumor-reactive CD8+ subsets, such as CD8+CD28− cells, which are linked to impaired immune function." (PMID 40958865, 2025). "In line with the best patient survivals, we propose that in response to tumor antigens within the lymph nodes, the activating checkpoint regulator CD28, as well as possibly others, represent a more activated T‐cell state in the HGSOC TIME, especially regarding the Triple‐I cluster." (PMID 40492347, 2025). "Trispecific antibodies (TsAbs), although still investigational, represent the next generation of immune redirection therapies, incorporating additional tumor antigens or co-stimulatory domains (e.g., CD28, 4-1BB) to mitigate antigen escape and enhance T-cell persistence." (PMID 40508128, 2025). "Similarly, dual-target TsAbs engaging CD3/CD28 and a tumor-associated antigen (TAA) are being developed to amplify immune responses in MM by co-engaging T-cell activation and tumor specificity in a single construct." (PMID 40508128, 2025). "Notably, PSCA-CARs containing 4-1BB motif exhibit superior antigen specificity and reduced T-cell exhaustion while maintaining tumor-killing potency comparable to CD28-based CARs." (PMID 41153826, 2025). "Thus, only the less activated CD8 T cells in the tumor have Cd28 expression that is unopposed by Ctla4." (PMID 41417245, 2025). "Lisocabtagene is comprised of a murine extracellular scFv of the FMC63 monoclonal antibody that binds to CD19 on tumor cells followed by a human IgG4 hinge region, CD28 transmembrane domain fused to the costimulatory molecule 4–1BB (CD137), and the T cell activation domain CD3ζ chain." (PMID 40061940, 2025). "Moreover, while the CD28 transmembrane portion (TM) is commonly used in CARs, CD8α TM or hinge regions have also proven advantageous in CARs against tumor antigens, and in our lab, against SARS-CoV-2 antigens." (PMID 40867541, 2025).
tumor (continued). "However, comparing patient‐matched tumor tissues showed CD28 was the highest expressed in the TIME for the Triple‐I cluster compared with the other tumor clusters." (PMID 40492347, 2025). "Thus, it was quickly replaced by the second-generation CAR-T that also contains a CD28 or 4-1BB costimulatory domain in addition to mediating more potent anti-tumor activity." (PMID 40821789, 2025). "Increasing CD28 costimulation in exhausted T cells can thus shift stem-like populations toward more robust, effector-like states, helping to overcome inhibitory signaling in chronic infection or tumor microenvironments." (PMID 40481182, 2025). "Finally, because programmed cell death protein 1 (PD-1) is known to inhibit CD28 signaling, we combined XmAb808 with an anti–PD-1 antibody to increase its antitumor efficacy against human tumor xenografts in mice." (PMID 39301613, 2025). "Importantly, the expression of CARMIL2QE molecules in Carmil2QECd28−/− mice was capable of substituting for CD28 engagement and led to complete tumor rejection." (PMID 40402149, 2025). "Furthermore, stimulation with anti‐CD3/CD28 increased LDH release in tumor‐border slices (1.4‐fold compared with the medium control)." (PMID 40952312, 2025). "Therefore, TSH was tandemly linked with either the CD28 or 4‐1BB costimulatory domain to construct CAR molecule (TSH‐CAR), and we comprehensively investigated the anti‐tumor efficacy and safety of TSH‐CAR‐T cells both in in vitro and in vivo experiments." (PMID 40985353, 2025). "As such, CD28-blocking therapeutics could impair tumour immune surveillance, providing a biological rationale for our observations." (PMID 39992258, 2025). "In addition, they are developing a CD28 co-stimulatory bispecific (REGN5668), which binds MUC16 and CD28 to provide a secondary activation signal to T cells at the tumor site." (PMID 40643516, 2025). "By redirecting inhibitory signals such as PD-L1 and TGF-β through synthetic receptors with activating domains (e.g., CD28, 4-1BB), CSRs could enhance the persistence and function of ILCs within immunosuppressive tumor microenvironments (TMEs)." (PMID 40963622, 2025). "Interestingly, despite the stimulatory effect of CD80 binding to CD28, it was found that deactivating CD80 reduces tumour growth and increases susceptibility to anti-CTLA-4 antibody treatment." (PMID 40725864, 2025). "Patients with pathological grade G2 exhibited a significantly lower proportion of tumor-infiltrating CD28+PD1−/CD8+ T cells compared to grade G1 patients (7.59% vs. 18.69%, p = 0.019), while no statistical difference was observed between grades G3 and G1 (9.56% vs. 18.69%, p = 0.052)." (PMID 40136325, 2025). "This complements the PD-1+CD8+ T cell findings: together, they paint a clear immune landscape—residual tumor risk is elevated in patients with an “exhausted” immune profile (high PD-1+CD8+ T cells) and reduced in those with an “activated” profile (high CD28+CD4+ T cells)." (PMID 41479903, 2025). "Overall, the combination of co-stimulatory molecules targeting CD28 is influenced by tumor type, tumor microenvironment, and CAR structure, and the optimal mode of co-stimulatory molecule tandem will need to be determined in the future based on specific tumors." (PMID 40181986, 2025). "Untransduced T cells were able to migrate into the tumor model (mean=22,334 cells, range=20,203-23,004 cells), but their numbers corresponded to only about 10% of the CD28-costimulated and 25% of the 4-1BB–costimulated L1CAM-CAR T cells that infiltrated the 3D tumor model." (PMID 41394860, 2025).
tumor (continued). "In contrast to CD28 signaling, SLAMF7 engagement reduced IL-10 secretion, a cytokine with well-established immunosuppressive functions, as well as IL-6 levels, which has been implicated in inflammation-driven tumor progression." (PMID 40909279, 2025). "The internal mechanisms that allow NKG2D/CD28&CAR-T cells to sustain their anti-tumor activity and youthfulness are multifaceted and may involve the intricate interplay between co-stimulatory signals and intracellular pathways." (PMID 40181405, 2025). "Brexucabtagene contains a murine extracellular scFv of the FMC63 monoclonal antibody that binds to CD19 on tumor cells followed by a human CD28α hinge and transmembrane domain fused to the costimulatory molecule CD28 and the T cell activation domain CD3ζ chain." (PMID 40061940, 2025). "However, CTLA-4 inhibitors act predominantly by enhancing the binding affinity between CD28 on T cells and B7-1/B7-2 on antigen-presenting cells (APCs), indirectly augmenting T cell anti-tumor activity." (PMID 40783512, 2025). "This combination of two tumor-targeted bispecific antibodies (one binding CD28 to replicate costimulation and the other binding CD3 to replicate TCR engagement) should reproduce two critical components of the synapse between cancer cells and T cells and thus enhance the immune response in the TME." (PMID 39301613, 2025). "These engineered molecules simultaneously bind tumor-associated antigens and immune receptors, such as CD3 on T cells, while incorporating co-stimulatory signals through molecules like 4-1BB (CD137), OX40 (CD134), or CD28." (PMID 39982231, 2025). "Cell–cell interaction analyses further demonstrate that T cells, macrophages, and dendritic cells communicate through regulatory axes such as PD-L1/PD-1 and CD80/CD28, while Tregs and plasmacytoid dendritic cells cooperatively contribute to tumor immune evasion." (PMID 41562080, 2025). "While exhaustion markers, such as PD-1 and CTLA-4, remained stably expressed across tumor progression, co-stimulatory molecules, including CD28 and ICOS, were significantly downregulated by 6 weeks, highlighting a state of persistent checkpoint signaling coupled with a loss of co-stimulation." (PMID 41278869, 2025). "We also speculate that this CD28 TCE format could be used to target tumor antigens too broadly expressed for safe use of CD3 TCEs, a class of immunotherapies known for the induction of cytokine release syndrome." (PMID 39301613, 2025). "In vivo experiments demonstrated that injection of colon cancer-derived exosomes could inhibit the activity and expansion of tumour-specific T cells and DCs, reduce the expression of CD28 and CD80/86, and promote tumour growth." (PMID 38302430, 2024). "Of note, a PD-L1/CD80 cis-heterodimerization has been reported on APCs, able to preserve the CD80 capacity to activate CD28, thereby supporting the sustained functionality of intra-tumor CD28+ T cells while repressing the inhibitory activity of PD-1 and CTLA-4." (PMID 39684559, 2024). "The protective effects observed for HLA DR+CD8br AC and CD28 on CD28+CD45RA+CD8br T cells suggest that these immune cells may be critical in mounting an effective anti-tumor immune response." (PMID 39450166, 2024). "It has been found that low expression of CD80 in tumor stem cells may inhibit the activation of the CD28 molecule on T cells in glioblastoma." (PMID 39575257, 2024). "We can speculate that the activation of CD28 is so crucial that CD80 as its ligand may bring more possibilities in tumor treatment." (PMID 39575257, 2024). "Second, provision of co-stimulation by Dap10 promoted greater anti-tumor activity than did CD28." (PMID 39566469, 2024). "Interestingly, the combination of CD28 and 4-1BB has shown the potential to simultaneously amplify anti-tumor effects and prolong the persistence of CAR-T cells." (PMID 39697210, 2024).
tumor (continued). "However, when ErbB dimers are also present, cytolytic activity, cytokine release, and anti-tumor activity are further enhanced via optimized dual CD28/4-1BB co-stimulation." (PMID 38745414, 2024). "While, after supplementing CD28 signal, it could be carefully observed that a few of tumor cells were surrounded by a fraction of T-cells and tightly bound to them, and induced perforated killing." (PMID 39158647, 2024). "Notably, recent investigations have reported a more significant accumulation of PD1+CD28+ T cells at tumor sites in NSCLC patients, likely mediated by the impact of CD28 on T-cell tissue localization following antigen priming." (PMID 39684559, 2024). "Finally, the ratio of PD-1/CD28 was significantly higher in BCC as compared to cSCC tumor cores (p = 0.028)." (PMID 39329753, 2024). "Our findings in this study revealed that the levels of circulating CD8+CD38+ T cells, CD8+CD28+ T cells, and NK cells are potential prognostic factors for tumor response and long-term survival in patients with HCC treated with TACE, administered with or without PD-1 inhibitors." (PMID 38404585, 2024). "Even if our previous experiments have demonstrated the superior proliferation capacity of IL-21R-TCR-T upon CD3/CD28 activation, the proportion analysis supported by scRNA-seq data further revealed the phenotype of proliferating T cells after tumor antigen stimulation in detail." (PMID 38643203, 2024). "This required the presence of a second activating αEpCAM–αCD3ε bsAb targeting an abundantly expressed tumor-associated antigen, whereas the mere crosslinking of EpCAM and CD28 by an αEpCAM–αCD28 bsAb was not sufficient." (PMID 39766150, 2024). "In these cases anti-PD-1/CTLA-4 blockade might enhance CD28 signaling and thereby could support T cell activation by local antigen presentation, thus improving tumour immune surveillance." (PMID 38440738, 2024). "This clinical phenomenon further strengthens our hypothesis regarding the close relationship between pTCD8+CD28- and tumour immunity." (PMID 38519706, 2024). "Also as expected, biologically active IL18 was detected when T cells expressing pCAR-H/T + GzB-IL18 were stimulated either on MDA-MB-468 tumor monolayers or by CD3+CD28 crosslinking." (PMID 38745414, 2024). "Therefore, in the context of cancer, the binding of CD86 to CD28 on T lymphocytes can assist in their activation, enhancing an effective anti-tumor immune response." (PMID 38791312, 2024). "During the first 2 weeks of treatment, mice treated with anti-αvβ3 CAR-T cells with a CD28 co-stimulatory domain showed rapid tumor regression, while in mice treated with CAR-T cells with a 4-1BB co-stimulatory domain, tumor volume decreased, but it was still detectable." (PMID 38339374, 2024). "In addition, we observed a positive correlation between pTCD8+CD28- levels and tumour immunity, which can be enhanced by immunotherapy." (PMID 38519706, 2024). "However, while enhancing T-cell activation and survival, CD28 also contributes to both positive and negative regulation of T cells, with multifaceted roles in protecting against intra-tumor RICD." (PMID 38891056, 2024). "However, following an increase in CD28 activation signal, the anti-tumor activity of T cells is enhanced." (PMID 39575257, 2024). "In cKO mice, the senescence inhibition markers CD27 and CD28 were induced in tumor-infiltrating CD8+ T cells, whereas the level of the metabolism-associated senescent cell marker β-gal was reduced, suggesting that knockout of Cbx4 enhances the anti-senescence capacity of T cells." (PMID 38994031, 2024). "We hypothesized that the extracellular domain of the PD1CD28 chimeric molecule’s PD-1 could bind to PD-L1 expressed on tumor cells, triggering activation of the intracellular co-stimulatory signaling domain of CD28 in the PD1CD28 chimeric molecule." (PMID 39352918, 2024).
tumor (continued). "These ICIs operate through distinct mechanisms: CTLA-4 inhibitors boost tumor-specific T-cell activation and proliferation by promoting CD28-mediated co-stimulation, while PD-1/PD-L1 inhibitors restore the function of tumor-infiltrating T cells by reversing negative signaling." (PMID 38541669, 2024). "Our data, in conjunction with findings from previous studies, indicate that CAR T-cells with a CD28 CSD exhibit rapid expansion and increased anti-tumor activity but are linked to shorter persistence and a greater tendency for T-cell exhaustion compared to those with a 4-1BB CSD." (PMID 39043633, 2024). "The expression of activation-specific genes (IFNG, GZMB, and TNFRSF9) and cell proliferation-specific genes (IL2, IL2RA, and CD28) decreased with the increasing rounds of tumor stimulation, especially from round 2 (the round in which tumor-killing ability begins to decline)." (PMID 39657666, 2024). "Additionally, the anti-tumor response of CD28-costimulatory CAR-T cells was validated in an animal model of CEA+ colorectal cancer." (PMID 37958672, 2023). "Also, in CAR T-cells, the presence of the co-stimulatory domains 4-1BB and CD28 was found to affect both their activation for tumor reduction and their survival for tumor elimination." (PMID 37998753, 2023). "CTLA-4 is another popular inhibitory immune checkpoint that could competitively bind CD80 and CD86 against CD28, interrupting the activation of anti-tumor immunity." (PMID 37305457, 2023). "However, nodal metastasis was associated with low levels of activated CD8 T cells expressing CD28 within the tumor (p = 0.08)." (PMID 36281585, 2023). "However, our recent study demonstrated that 1α,25(OH)2D3 pretreated γδ T cells, activated by anti-CD3/CD28 antibody or tumor cells, showed increased Th1 cytokine production." (PMID 37908738, 2023). "However, CARs with CD28 co-stimulatory domains demonstrated earlier tumour growth control compared with those with 4-1BB co-stimulatory domains, independent of the affinity of the scFv." (PMID 37291434, 2023). "Conversely, the presence of CD28, which was associated with poor polyfunctionality in the periphery, increased the functional capability of PD1+ T cells with the passage to the NT and tumor site." (PMID 37898752, 2023). "Similarly, small changes in the CAR CD3ζ or CD28 signaling domains reducing activation are known to promote memory differentiation and tumor rejection." (PMID 36732507, 2023). "However, NK cells expressing chimeric receptors will reduce their anti-tumor effects after adding a costimulatory domain CD28, OX40 or 4-1BB between DNAM1 and CD3ζ." (PMID 37404752, 2023). "pCD28-siRNA-PD-1 elevated CD28 expression and suppressed PD-1 expression in tumor tissues." (PMID 37767098, 2023). "Remarkably, the identified pre-exhausted KLRG1+EOMES+CD28+ cluster was well represented also in periphery, sharing a phenotypical and functional signature with tumor infiltrating T cells, thus likely providing a feasible tool for the identification of responsive patients." (PMID 37898752, 2023). "Despite the increased PD1 levels, an improved PD1+CD28+ T-cell polyfunctionality was observed with the transition from periphery to tumor site, associated with lack of TIGIT, TIM-3 and LAG-3, but not with Ag-experienced-marker CD11a." (PMID 37898752, 2023). "At the same time, an interesting event is worthy of focus: In addition to MHC molecules, LPPC/MP complexes could also provide costimulatory B7 molecules to activate host immunity against metastatic tumor cells by engaging CD28 on T-cell." (PMID 36691089, 2023). "FAK depletion can lead to tumor regression by increasing the number of CD28+ T cells in the TME." (PMID 37749625, 2023). "In particular, the absence of CD28 was associated with a gradual decline in terms of granzyme-B (GrzB) production from peripheral blood to the NT tissue and the tumor site." (PMID 37898752, 2023).